EGFR (epidermal growth factor receptor)
Diseases named in the same sentence as EGFR in open-access papers (continued):
Sharing a sentence is not in itself a finding about the gene and the disease.
lung cancer (continued). "The potential of fluorescein-based Smartprobe imaging in lung cancer has been demonstrated by targeting epidermal growth factor receptor mutations in cell line xenograft mouse model and in ex vivo human lung cancer tissue for visualising matrix activity." (PMID 33060152, 2021). "This study investigated the frequencies, clinical characteristics, therapeutic efficacies, and genetic profiles of lung cancer patients with EGFR and ALK co-mutations." (PMID 34654390, 2021). "For lung cancers, in particular, there are high failure rates for mutation evaluation (i.e., 32%, 27%, and 35% for EGFR, KRAS, and ALK tests, respectively) with image-guided percutaneous transthoracic core-needle biopsies." (PMID 34873529, 2021). "Our study results showed that ANXA1 plays critical roles in chemosensitivity to EGFR-TKI in lung cancer cells with the EGFR mutation." (PMID 34439260, 2021). "Based on this, a KRAS gene mutation in A549 EGFR‐wild‐type lung cancer cells actively promotes over‐phosphorylated EGFR‐AKT levels, keeping its over‐activated level even when using EGFR‐TKIs treatment." (PMID 33433063, 2021). "The good sensitivity and specificity of the rapid detection of EGFR mutations using the IdyllaTM system were previously reported in other publications on lung cancer, as well as on other cancers such as melanoma and colorectal cancer." (PMID 34898548, 2021). "The arrival of subsequent generations of tyrosine-kinase inhibitors (TKIs) has significantly broaden the EGFR-mutated lung cancer therapeutic landscape." (PMID 34306781, 2021). "In contrast to lung cancer, the EGFR mutations are rare in breast cancer, with a frequency of no more than 5–6%." (PMID 33572326, 2021). "Ahn used CE-T1 MRI to predict the EGFR mutation in histologically certified primary lung cancer patients’ brain metastases (33 with EGFR WT, 29 with EGFR mutation)." (PMID 34722274, 2021). "In any case, we think that this is a very important finding because single treatment with anti-MET TKIs in patients with EGFR-mutated and MET-amplified lung cancer will restore EGFR activity." (PMID 34298655, 2021). "Another study revealed the presence of activating mutations in the EGFR‐encoding gene in CTCs collected from lung cancer patients receiving EGFR‐targeting tyrosine kinase inhibitors (TKIs)." (PMID 33448107, 2021). "This review focuses specifically on the latest treatments for EGFR mutation-positive lung cancer and the strategies aimed at overcoming drug resistance; moreover, we discuss the prospects for their use in clinical settings." (PMID 34831415, 2021). "The analysis of volatile metabolites from malignant pleural effusion has high discrimination accuracy for lung cancer and EGFR mutation." (PMID 34193905, 2021). "This study revealed that assessing the risk of EGFR mutation-positive lung cancer just by EGFR mutation-positive proportions in tested patients, ignoring underlying population incidence, can be misleading." (PMID 33961689, 2021). "A subset of non–small cell lung cancer (NSCLC) is driven by activating somatic EGFR mutations, most commonly short in-frame deletions of exon 19 (del19) or missense mutations resulting in the amino acid substitution L858R." (PMID 34516823, 2021). "The therapeutic value of our strategy is demonstrated by programmed silencing of critical targets associated with various diseases, including EGFR/KRAS in lung cancer, EGFR/TNC in glioblastoma and PTP1B in obesity." (PMID 33782530, 2021). "The majority—but not all—of cases that received poziotinib or mobocertinib in this compiled cohort of advanced lung cancers harboring EGFR exon 20 insertion mutations with G770 equivalence had radiographic responses." (PMID 34944068, 2021). "When cancer cells were cocultured with stromal cells, the cancer cells showed resistance to chemotherapy 9 and EGFR tyrosine kinase inhibitors in lung cancer cells with EGFR mutations." (PMID 34646392, 2021).
lung cancer (continued). "Lastly, we review the potential of exosomes to be used as novel biomarkers for the purpose of diagnosing cancer at an early stage, in addition to assessing prognosis, and as therapeutic predictors in EGFR-mutated lung cancer." (PMID 33855679, 2021). "To further study these three putative erlotinib‐sensitizing chemicals (SJ‐172550, nutlin‐3, and carfilzomib), we performed efficacy testing with a human lung cancer PDX model having an EGFR T790M mutation (i.e., comprised of erlotinib‐resistant cells)." (PMID 33188726, 2021). "Epidermal growth factor receptor (EGFR) tyrosine kinase inhibitors (TKIs) serve as the standard of care for the first-line treatment of patients with lung cancers with EGFR-activating mutations." (PMID 34202566, 2021). "In H1975 and H1650 lung cancer cells with EGFR mutations, the combination treatment of ANXA1 siRNA and Osimertinib resulted in significantly decreased survival cells compared to the Osimertinib group." (PMID 34439260, 2021). "For lung cancer patients with EGFR mutations, targeted therapy based on EGFR tyrosine kinase inhibitors (EGFR‐TKIs) is widely used in clinical treatment." (PMID 33931980, 2021). "The onset of mutations causing resistance to EGFR tyrosine kinase inhibitors (EGFR-TKIs) represents a clinical challenge for the treatment of lung cancer." (PMID 33537086, 2021). "Another report has shown that the detection of EGFR activating and T790M mutations in EV RNA and free circulating DNA offers clinically meaningful sensitivity (> 0.9) for lung cancer studies." (PMID 34855021, 2021). "In lung cancer, the deletion mutation in exon 19 and point mutation in exon 21 (L858R) represent 90% of EGFR mutations." (PMID 33639678, 2021). "Different from the high frequency of EGFR mutation in lung cancer, a high percentage (50%) of BRAF mutation was found in BA." (PMID 34663408, 2021). "Results of our current comprehensive study of cytokines did reveal that the transfection of miR‐1 into three different human lung carcinoma cell lines harboring EGFR mutations significantly decreased the expression of CCL5, CXCL10, IL‐6, IL‐8, and TNF‐α." (PMID 33305905, 2021). "In lung carcinoma cell lines, a strong association between p-EGFR and miR-21 levels and the suppression of miR-21 by the EGFR-TKI AG1478 indicates that EGFR signaling positively controls miR-21 expression." (PMID 34830377, 2021). "Results of our present study reveal that miR‐1 transfection into human lung carcinoma cell lines harboring EGFR mutations does inhibit the migration of human monocytes." (PMID 33305905, 2021). "On the other hand, some mutated EGFR lung cancers induce resistance to EGFR-TKIs (gefitinib and erlotinib)." (PMID 32850327, 2020). "The introduction of anti-EGFR antibodies and EGFR tyrosine kinase inhibitors (TKIs) in clinical practice drastically improved the prognosis of patients affected by various cancer types, especially lung cancer, the first leading cause of cancer death worldwide." (PMID 32517369, 2020). "In the present cohort, there was a lung adenocarcinoma patient who underwent surgical lung cancer resection, and tumor tissues had an EGFR 19Del mutation detected by NGS." (PMID 32711494, 2020). "Lung cancer cells harbor various gene mutations in the epidermal growth factor receptor (EGFR) gene." (PMID 32605095, 2020). "Inherited susceptibility to lung cancer has also been demonstrated in rare families with a germline EGFR mutation, the majority of them harboring a somatic second hit." (PMID 32295625, 2020). "The response to icotinib in advanced non‐small cell lung cancers (NSCLC) with EGFR uncommon mutation (EGFRum) is unclear." (PMID 31692291, 2020). "This study investigated the clinical characteristics of EGFR-mutated lung cancer patients harboring the T790M substitution resistant to EGFR-TKIs, as well as the advantages of rebiopsy and liquid biopsy for these patients." (PMID 33008313, 2020).
lung cancer (continued). "The epidermal growth factor receptor (EGFR) tyrosine kinase inhibitor (TKI) erlotinib is used in the treatment of non–small cell lung cancer (NSCLC) patients harboring somatic EGFR mutations, including exon 19 deletion and exon 21 L858R substitution." (PMID 32266784, 2020). "A large-scale Chinese study of 5387 lung cancer patients found that EGFR-mutated subjects have a significantly higher risk for LM versus wild-type subjects (9.4% vs. 1.7%)." (PMID 32736566, 2020). "Among the 105 participants, germline EGFR mutations were found in 63% of patients with EGFR T790M detected in lung cancer tissue at diagnosis, and in 62% (16 of 27) and 44% (4 of 9) of first- and second-degree relatives of germline carriers, respectively." (PMID 32104210, 2020). "Accordingly, some experts pointed out that TKI was becoming a favorable treatment, especially for patients with EGFR mutation of BMs of lung cancer." (PMID 32883221, 2020). "Given the frequency of EGFR mutations in lung cancer patients, we treated EGFR-mutated (E746-A750 deletion) HCC827 human lung cancer cells with the mutated EGFR inhibitor icotinib." (PMID 31649305, 2020). "We also monitored the proliferation of EGFR mutation lung cancer cells H1650, H1975, and HCC827 under treatment with rHuEPO and Afatinib versus Afatinib alone." (PMID 32922549, 2020). "Compared with chemotherapy, EGFR-TKI administration results in a high response rate in patients with EGFR mutation-positive lung cancer; in particular, osimertinib has a response rate of 80%." (PMID 33260352, 2020). "EGFR mutation is significantly associated with lung cancer patients developing brain metastases 12, suggesting elevated EGFR signaling is important for brain metastasis." (PMID 33042262, 2020). "An EMT-independent mechanism for the biological functions of ZEB1 has also been reported in epidermal growth factor receptor (EGFR)-mutated lung cancer cells." (PMID 33097763, 2020). "Mutations in the gene encoding EGFR are critical because this receptor is used as a target in lung cancer treatment." (PMID 33261184, 2020). "Among them, epidermal growth factor receptor‐tyrosine kinase inhibitors (EGFR‐TKIs) benefit lung cancer patients with activating EGFR mutations." (PMID 32003107, 2020). "The results of our retrospective study offer some clinical insights on advanced lung cancer harboring sensitive EGFR mutations." (PMID 32092879, 2020). "Our results show that FBLN1 suppresses EGFR activation, and that loss of FBLN1C/FBLN1D (as seen in lung cancers) can promote EGFR dependent cellular function." (PMID 32719793, 2020). "This dataset was a lung cancer cohort, containing normal individuals, those with epidermal growth factor receptor (EGFR) mutations, anaplastic lymphoma kinase (ALK) mutations, RAS mutations and wild type lung adenocarcinoma at different stages." (PMID 32708433, 2020). "Accordingly, this study investigated the characteristics of EGFR-mutated lung cancer patients harboring the T790M substitution that was resistant to EGFR-TKIs in order to identify patients with positive features who require tissue and liquid rebiopsy." (PMID 33008313, 2020). "Afatinib is currently approved for first-line treatment of patients with EGFR-mutation-positive lung cancer." (PMID 32066410, 2020). "One example is the treatment of lung-cancer patients positive for Epidermal Growth Factor Receptor (EGFR) mutations, which are now treated with EGFR tyrosine kinase inhibitors as first line of therapy." (PMID 31991800, 2020). "Currently, the National Health System in Greece provides access to EGFR mutation testing for lung cancer patients via tissue biopsy." (PMID 32599934, 2020). "The development of epidermal growth factor receptor (EGFR) inhibitors is one of the difficulties in the treatment of lung cancer with EGFR mutation." (PMID 32477114, 2020).
lung cancer (continued). "To date, only one of the very few FDA-approved ccfDNA-based tests with clinical utility is the Cobas® EGFR Mutation Test v2 (Roche Molecular Systems Inc., Pleasanton, CA, USA) detecting 42 EGFR hotspot mutations in ccfDNA from patients with lung cancer." (PMID 33081150, 2020). "On the other hand, we demonstrated that in AXL-low-expressing EGFR-mutated lung cancer cells, osimertinib exposure increased protein expression and phosphorylation of IGF-1R and thereby restored the survival signal mainly via Gab1 and IRS1 to emerge tolerant." (PMID 32929081, 2020). "Several studies have previously demonstrated the survival benefit of both EGFR‐TKI treatment and chemotherapy in patients with non‐small cell lung cancer (NSCLC) harboring EGFR mutations." (PMID 32077630, 2020). "Advances to date have largely been based on a single gene - single drug paradigm delivered through a limited genomic test (a ‘companion diagnostic’), as exemplified by EGFR inhibitor therapy for EGFR-mutant lung cancers." (PMID 33144218, 2020). "Concerning the main alterations clinically relevant in lung cancers, about 9% of patients had an AC harboring a classical EGFR mutation (exon 19 deletions or the exon 21 point mutation L858R)." (PMID 33172431, 2020). "There is a great difference in the EGFR gene mutation phenotype of lung cancer in China compared with that in Western countries." (PMID 32191394, 2020). "A positive effect of bisphosphonate administration on survival of EGFR mutated lung cancer patients submitted to TKIs was previously observed in 3 published series." (PMID 33282740, 2020). "Through gene sequencing, it can be seen that lung cancer-related genes such as epidermal growth factor receptor gene mutation, c-MET, ROS1, KRAS, and BRAF, play an extremely important role in diagnosis and treatment of lung cancer." (PMID 32316985, 2020). "EGFR mutations such as L858R or T790M-L858R (double mutation) are found in lung cancer patients and are known to be sensitive or resistant to EGFR-TKIs, respectively." (PMID 33092268, 2020). "The purpose of this study was to investigate the clinical characteristics of EGFR-mutated lung cancer patients harboring the T790M substitution that were resistant to EGFR-TKIs." (PMID 33008313, 2020). "In East Asia, the prevalence of lung cancer with EGFR mutations is more common with a proportion of 30%–40%21." (PMID 32944405, 2020). "The abundance of tumor infiltrating CD8 T cells is an important parameter for antitumor effect of PD‐1/PD‐L1 immune checkpoint inhibitors, which is less in epidermal growth factor receptor (EGFR) mutation than wild‐type non‐small cell lung cancer (NSCLC)." (PMID 32500560, 2020). "Liquid biopsies are mostly done in our institution for the detection of EGFR T790M resistance mutations in the context of lung cancer." (PMID 33029526, 2020). "The most common oncogenic driver mutation in lung cancer is epidermal growth factor receptor (EGFR) mutation, which characterizes approximately 40–55% of all NSCLC in Asian patients." (PMID 32385709, 2020). "It is known that lung cancer patients develop resistance to TKI therapy due to secondary mutations in the EGFR gene or activation of alternative signaling pathways." (PMID 32170113, 2020). "We also showed that TAS-116 was effective against EGFR-mutated lung cancer by decreasing EGFR in endosomes." (PMID 31857719, 2020). "To confirm the activities of TAS-116 on other tyrosine kinases, we evaluated growth inhibition by TAS-116 using several lung cancer cell lines, including EGFR-wild-type and EGFR-mutated cell lines." (PMID 31857719, 2020). "We screened cfDNA from lung cancer patients for two clinically-relevant mutations namely T790M and L858R in tyrosine kinase domain of EGFR gene." (PMID 33067539, 2020).
lung cancer (continued). "In conclusion, we uncovered the mechanism by which AXL-low-expressing EGFR-mutated lung cancer cells demonstrated tolerance to osimertinib." (PMID 32929081, 2020). "One study compared the frequency of BMs by histologic subtypes and EGFR mutation status of lung cancers." (PMID 32984041, 2020). "EGFR gene mutations and EGFR protein overexpression are associated with tumor growth through activation of downstream pathways, especially in lung cancer." (PMID 32359357, 2020). "Another study showed that hypoxia induces upregulation of Mig-6 which results in dormancy and resistance to EGFR-TKIs in primary cultured lung cancer cells with EGFR mutations." (PMID 32552717, 2020). "Cytoplasmic ERβ1 was associated with poor progression-free survival in lung cancer patients treated with EGFR TKIs." (PMID 33585221, 2020). "Here, we aimed to evaluate the predictive and prognostic role of EGF+61A>G SNP in lung cancer from Brazilian EGFR‐mutated TKI‐treated patients." (PMID 32881389, 2020). "Previous reports have indicated that the incidence of epidermal growth factor receptor (EGFR) mutations is high in Asian populations, reaching 30% in non‐small cell lung cancer (NSCLC) patients and 50% in those with adenocarcinoma." (PMID 32508032, 2020). "In the cohort of young patients with LUAD from our center, we observed obvious heterogeneity between our cohort and the population of lung cancer worldwide; 73.24% of our young patients harbored EGFR or ALK mutations." (PMID 32967633, 2020). "In lung cancer, the use of the Cobas Epidermal Growth Factor Receptor (EGFR) Mutation Test v2 (Roche, Basel Switzerland) is approved for the detection of EGFR variants by cfDNA analysis by the Food and Drug Administration (FDA) for treatment selection." (PMID 32251424, 2020). "A phase II multicenter, open‐label, single‐arm trial has been initiated to evaluate the efficacy and safety of afatinib and bevacizumab combination as salvage therapy for EGFR‐mutated lung cancer in patients previously treated with osimertinib." (PMID 32495514, 2020). "Contrast-enhanced T1-weighted image radiomics of brain metastases predicted the EGFR mutation status of lung cancer BMs with good diagnostic performance." (PMID 32483122, 2020). "The sensitivity of plasma EGFR mutation detection using PCR methods was recently reported to be 10% to 22.2% in stage I-IIIA lung cancer." (PMID 32196518, 2020). "3rd-generation epidermal growth factor receptor-tyrosine kinase inhibitors (EGFR-TKIs), including osimertinib, have reasonable efficacy in non–small-cell lung cancers (NSCLC) with EGFR mutations." (PMID 31183631, 2020). "The “good” quality studies on salivary biomarkers and lung cancer are those demonstrating an association with EGFR, the 5 mRNA, microbiota and cytokines." (PMID 32040469, 2020). "Among several EGFR mutations, two hotspot mutations, namely L858R and Exon 19-del mutations, comprise of the vast majority in patients with lung cancer." (PMID 32344833, 2020). "The frequency of epidermal growth factor receptor mutation-positive lung cancer was highest in this group." (PMID 33218332, 2020). "To date, most studies using radiomics for the prediction of EGFR mutation status in NSCLC are based on chest CT images, whereas few studies about the relationship between PET or PET/CT radiomics features and EGFR mutation status in lung cancer are conducted." (PMID 33134170, 2020). "All these data suggest that BASP1-abundant lung cancer cells facilitate EGFR signaling amplification than BASP1-deficient cells." (PMID 33042262, 2020). "EGFR-mutated lung cancer is a special molecular subgroup of lung cancer in which most patients benefit from treatment with EGFR-TKIs67." (PMID 33219256, 2020). "Considering that these lung cancer patients receive a tyrosine kinase inhibitor aimed at their specific EGFR mutation, the expression of the mutated gene and its products is diminished both in malignant and normal cells, such as those found in skin." (PMID 33015988, 2020).